CRP (C-reactive protein)
Diseases named in the same sentence as CRP in open-access papers (continued):
Sharing a sentence is not in itself a finding about the gene and the disease.
COVID-19 (continued). "Patients with severe or critical COVID-19 had lower lymphocyte count (1100 vs 1400 cells/mL; p<0.001), higher C-reactive protein (CRP) (27.5 mg/L vs. 6 p<0.001), D-dimer (0.9 vs. 0.5 μg/ml; p<0.001) and ferritin levels (780 vs. 344 ng/mL; p<0.001), respectively." (PMID 34624038, 2021). "Consistently, the CRP level was also found as one of the variables most predictive of respiratory failure and of the need for mechanical ventilation in 89 adults hospitalized for COVID-19." (PMID 34506514, 2021). "Blood oxygen saturation, age, high-sensitivity troponin, c-reactive protein, and lactate dehydrogenase were identified as the strongest predictors of poor outcome available at time of ED presentation in COVID-19 with highly comparable prognostic utility in overall and respiratory controls." (PMID 34204453, 2021). "Besides, the results of Pearson correlation analysis showed that serum LDL-C levels of COVID-19 patients was negatively correlated with CRP level, but has nothing to do with hs-CRP, procalcitonin." (PMID 34124081, 2021). "CRP was a queried DEG and a highly expressed gene found to be associated with COVID-19 severity." (PMID 35154611, 2021). "Recent work by the Wuhan team concluded that serum levels of CRP could be used independently to assess and predict the severity of COVID-19." (PMID 33808934, 2021). "CRP was significantly higher in COVID-19 patients (p < 0.001)." (PMID 34402750, 2021). "Furthermore, we need to be more vigilant to the levels of C-reactive protein and neutrophils, once cancer patients are infected with COVID-19." (PMID 34094950, 2021). "Several parameters have been determined, including clinical signs and hematological laboratory data comprising blood count, D-dimer, CRP, cytokines profiling, and qualitative and quantitative PCR assays for the virus load to evaluate the efficacy of the drug combinations used in COVID-19 therapy." (PMID 33628506, 2021). "A study conducted in China on 27 patients with COVID-19 showed that CRP levels positively correlated with the diameter of the lung lesion and might reflect the severity of the disease." (PMID 33787678, 2021). "This novel three-gene signature discriminates viral infections, including COVID-19, from other emergency infection presentations in adults, outperforming both leukocyte count and CRP, thus potentially providing substantial clinical utility in managing acute presentations with infection." (PMID 34423323, 2021). "Although an elevation of CRP is generally associated with bacterial rather than viral infections, elevated CRP levels have been observed in COVID-19 patients as well as in severe progression of other respiratory viral diseases such as influenza." (PMID 34307391, 2021). "Besides suPAR, LDH, CRP, neutrophil count, neutrophil-to-monocyte and neutrophil-to-lymphocyte ratio, body mass index and chronic renal failure were discriminators of COVID-19 severity and/or predictors of length of hospitalisation." (PMID 34926532, 2021). "Analysis of the receiver operating characteristic (ROC) curve found that CRP could be used as an independent factor in predicting the severity of COVID-19." (PMID 33968148, 2021). "Compared with the non-COVID acute/subacute thromboembolic patient group (N = 40), serum D-dimer and CRP levels were found to be significantly higher and lymphocyte counts were significantly lower in COVID-19-positive acute/subacute thromboembolism cases (p = 0.02, 0.005, and <0.001, respectively)." (PMID 34435041, 2021). "It is therefore noteworthy that severe COVID-19 accompanied by ARDS is distinguishable from mild COVID-19 by additional clinical parameter diagnostics for bacterial infection, including elevated ferritin, C-reactive protein and procalcitonin levels, as well as eosinopenia." (PMID 33672738, 2021). "First, CRP in the early stage of COVID-19 has been reported to be positively correlated with lung lesions and may thus be a biomarker of the disease severity." (PMID 34506514, 2021).
COVID-19 (continued). "In severe COVID-19-induced cytokine storm syndrome with organ failure, infliximab was reported to exert a rapid and at least temporary decrease in proinflammatory cytokines and other inflammatory markers (e.g., CRP and LDH) with clinical improvement." (PMID 34578460, 2021). "In 84 Japanese patients admitted with mild to moderate COVID-19, advanced age, lymphopenia, and obesity, but not CRP, were associated with increased oxygen requirements." (PMID 34441877, 2021). "In addition, patients with severe COVID-19 outcomes have exhibited abnormally high C-reactive protein levels, lactate dehydrogenase, and neutrophils, implying an inflammatory response and severe pneumonia." (PMID 35284429, 2021). "This study found similar findings, with higher CRP rates estimated upon admission for COVID-19/Non-COVID individuals with high mortality risk." (PMID 34573923, 2021). "Importantly, the evidence from this study suggests that CRP and gut microbiota diversity are prognostic biomarkers for severe COVID-19." (PMID 34349747, 2021). "The COVID-19-positive group in that previous study had higher CRP levels, similar to those of our study; thus, we can conclude that cortisol elevation may be related to disease severity." (PMID 34190873, 2021). "The values we report for CRP in our solid organ transplant recipient population are similar to levels reported in a general cohort of critically ill Chinese patients with COVID-19 = (average CRP 10.5 ± 1.27 mg/dL), as well as reported critically ill solid-organ transplant patients in New York." (PMID 33034239, 2021). "In COVID-19, adiposity is associated with a preponderance of pro-inflammatory cells in hypertrophic adipocytes, that contribute to increases in serum cytokines, such as IL-6, TNF-alpha and CRP." (PMID 34383798, 2021). "We found that C-reactive protein, lactate dehydrogenase, creatinine, white-blood cell count, D-dimer and lymphocyte count showed temporal divergence between COVID-19 patients hospitalized in the general floor that were upgraded to ICU compared to those that were not." (PMID 33976972, 2021). "Finally, we found that cytokine levels were acutely increased in severe and critical COVID-19 patients, particularly IL-6, IL-10, CRP and PCT." (PMID 33735325, 2021). "Interestingly, C-reactive protein has been a commonly measured marker and a reliable predictor of severity during the COVID-19 pandemic." (PMID 34673782, 2021). "Cytokine storm, hyperinflammation, multiorgan failure, and acute respiratory distress syndrome were described in COVID-19 patients with high fever, dyspnea, lymphopenia, and high serum ferritin, D-dimers, C-reactive protein (CRP), and cytokines, including IL-1b, IL-6, and TNF-α." (PMID 34578460, 2021). "Most hospitalized patients with COVID-19 have elevated CRP levels." (PMID 34567235, 2021). "In terms of laboratory parameters, a significant difference was found in white blood cell, CRP, and D-dimer values between the groups, with the highest values seen in Group 3 (included patients diagnosed with COVID-19 with one or more other chronic diseases in addition to hypertension)." (PMID 34704822, 2021). "C-reactive protein, lactate dehydrogenase, N-terminal pro–B-type natriuretic peptide, and interleukin-6, which are used to evaluate COVID-19 severity, may already be increased in HF patients, including patients on LVAD support." (PMID 34769350, 2021). "Our findings show how, among the variables assessed in our study, CRP was the inflammatory biomarker which varied more significantly during the course of COVID-19 in obstetric patients, supporting its employment as a tool to monitor the evolution of the disease." (PMID 34172816, 2021). "Hence, the current study aims to evaluate the correlation between CRP levels and disease progression to provide a reference for the clinical management of COVID-19 patients." (PMID 33968148, 2021).
COVID-19 (continued). "The aim of this systematic review was to investigate the effect of the level of some laboratory factors (C-reactive protein (CRP), creatinine, leukocyte count, hemoglobin, and platelet count) on the severity and outcome of coronavirus disease 2019 (COVID-19)." (PMID 33726761, 2021). "Additionally, high BMI, elderly age, high CRP and 4C-scores correlated with the severity and mortality of COVID-19 patients." (PMID 34822419, 2021). "Previous works have documented that CRP might play a role in predicting a higher severity of COVID-19 in the early stages, before the development of CT findings." (PMID 34568363, 2021). "Another study proposed CRP as an early predictive marker of severe COVID-19." (PMID 34439469, 2021). "In line with our results, Spanish investigators recently provided a protocol for outpatient management for patients with COVID-19, stating that CRP and D-dimer levels could extract groups with very low rates of admission and no mortality." (PMID 34300252, 2021). "Due to there being no precise and specific antiviral medicine for this emerging illness, MSCs were applied in several critically ill COVID-19 patients, contributing to the decline of plasma C reactive protein (CRP), aspartic aminotransferase, creatine kinase activity, and myoglobin." (PMID 33955590, 2021). "Inflammatory biomarkers such as C-reactive protein (CRP), interleukin-6 (IL-6), and procalcitonin, often used in critically ill patients, have been proposed as risk stratification tools in the context of COVID-19." (PMID 34501358, 2021). "Moreover, it has been observed that the most severe cases of COVID-19 are associated with a reduction in CD4+ T, T-lymphocytes, CD8+ T cells and an increase in levels of C-reactive protein, D-dimer, ferritin, IL-6, IL-2R40." (PMID 34824310, 2021). "The CORACLE Registry confirmed the negative prognostic role of older age, cardiovascular diseases, COPD, immunosuppression, diabetes, patients presenting with an eGFR < 30 mL/min/1.73 m2, high values of CRP and a low PaO2/FiO2 ratio upon admission of COVID-19 patients on hospital mortality." (PMID 34062864, 2021). "Our CRP results are similar to one other territory-wide study that was performed in Hong Kong 19 and another smaller study from Taiwan20, which directly compared laboratory markers with other non-COVID-19 respiratory infections." (PMID 34244563, 2021). "The treatment was also associated with normalization of lymphocyte count and reduction of CRP levels, suggesting that tocilizumab could be an effective agent in COVID-19 treatment." (PMID 34063964, 2021). "Combination of eosinopenia with elevated CRP could effectively triage suspected patients with COVID-19 from other patients with fever." (PMID 34548411, 2021). "Concerning severe-to-critical COVID-19 patients at baseline, retrospective studies on TCZ efficacy showed improved outcomes at various time-points after admission, being associated to critical disease only in one study or to CRP>15 mg/dl at baseline only." (PMID 34506608, 2021). "Levels of IL-6, CRP, absolute lymphocyte count, neutrophils and neutrophil-to-lymphocyte ratio obtained upon admission may help predict the severity of COVID-19." (PMID 34567235, 2021). "The level of CRP in patients with COVID-19 presenting cardiac damage is higher than that in patients without cardiac damage; furthermore, an elevated CRP level is associated with an adverse outcome in patients with HF." (PMID 33404925, 2021). "The biomarkers (CRP and NLR) may be linked with dynamic changes of renal function in COVID-19 patients who are asymptomatic or have mild symptoms." (PMID 34069451, 2021). "Research has found that CRP level is positively correlated with the diameter of lung lesions and could reflect disease severity of COVID-19 patients." (PMID 34122620, 2021).
COVID-19 (continued). "Furthermore, we also found that C-reactive protein, leukocytes, neutrophils, and NLR were associated with AKI in COVID-19 patients, corroborating those findings reported by other studies." (PMID 34033655, 2021). "Levels of clinical biomarkers associated with COVID-19, including CRP and D-dimer, were higher in the severe compared with non-severe disease cohorts." (PMID 34458849, 2021). "The pathogenesis of severe forms of COVID-19 is characterized by hyperinflammatory syndrome, i.e. a cytokine storm; with overproduction of inflammation-related molecules such as interleukin-6 (IL-6), C-reactive protein (CRP), and ferritin." (PMID 34038475, 2021). "Further studies are needed to determine whether drugs aimed at normalizing CRP levels may improve COVID-19 survival." (PMID 34506514, 2021). "Hence, this present study aimed at measuring plasma levels of FT3, FT4, TSH and Hs-CRP in COVID-19 patients and apparently healthy uninfected controls." (PMID 34650659, 2021). "Moreover, some studies have shown that most of the patients infected with COVID-19 displayed lymphocytopenia, elevated D-dimer levels, CRP, and, in some cases, elevated liver enzymes such as AST and ALT." (PMID 32892540, 2021). "CRP was significantly higher in the ICU COVID-19 patients (p < 0.001)." (PMID 34071149, 2021). "In the present single-center study, we analyzed clinical and radiological data, CRP-values, platelet counts and coagulation parameters of 274 COVID-19 patients with pneumonia of different severity in a comparative approach between the two waves of infection focusing on the case of Romania." (PMID 34063243, 2021). "This may relate to the cytokine storm syndrome accompanying severe COVID-19, better reflected by strong hyperferritinemia than increased CRP." (PMID 33956870, 2021). "Moreover, SpO2, D-dimer levels, and CRP/Alb ratio on admission were independent predictors of progression to critical disease or death in patients with severe COVID-19." (PMID 34900028, 2021). "The hospitalized COVID-19 patients with statins showed a lower mean of C-reactive protein (103 mg/L vs. 124.7 mg/L, p < 0.001) D-dimer (2.4 μg/mL vs. 2.8 μg/mL, p 0.37), and WBC count (7.8 × 103/μL vs. 8.5 × 103/μL, p < 0.01), in comparison to non-statin users." (PMID 34604534, 2021). "Additionally, they revealed that confirmed COVID-19 patients had more likely leukopenia, hypoalbuminemia, increased C-reactive protein and lactate dehydrogenase levels." (PMID 34812057, 2021). "A full viral panel including COVID-19 C-reactive protein and serology could only isolate the Influenza B virus." (PMID 34231814, 2021). "Our data demonstrate that PD-L1 might be useful to stratify COVID-19 patient prognosis as high levels of sPD-L1 correlated with validated prognostic biomarkers especially lymphopenia and high levels of CRP as well as with an increase of LOS and mortality rate." (PMID 34163490, 2021). "Likewise, some investigations have confirmed the utility of CRP as prognostic factor in COVID-19 since it serves as an early marker of infection, inflammation, and tissue damage." (PMID 34300279, 2021). "Other soluble factors are also increased in patients with COVID-19, including C-reactive protein (CRP), procalcitonin (PCT), lactate dehydrogenase (LDH), alanine aminotransaminase (ALT), aspartate transaminase (AST), troponin, D-dimer and fibrin degradation products." (PMID 34829345, 2021). "And HDL-C level was negatively correlated with CRP level in COVID-19 patients." (PMID 34124081, 2021). "CRP levels have been shown to be predictive of more severe COVID-19 disease, thus fitting with work suggesting thromboembolic complications are more frequent in patients with more severe COVID-19." (PMID 34319144, 2021).
COVID-19 (continued). "For COVID-19 monoinfected patients described in the main study, most of the patients had normal leukocyte count (72.1%), higher CRP (100%), higher procalcitonin (74%), higher D-dimer (67%), elevated AST (66%), elevated ALT (37%), nearly normal urea, and creatinine." (PMID 34597315, 2021). "Simply put, COVID-CS should be considered in a patient with a confirmed diagnosis of COVID-19, if there is a rapid deterioration of the general condition, persistent fever lasting than three days, progressive increase in serum CRP, ferritin, and D-dimer values." (PMID 34803441, 2021). "Moreover, obese patients with COVID-19 were more likely to have secondary bacterial infection and relatively high levels of CRP, which also contributed to the development of critical illness." (PMID 33746594, 2021). "Taken together, while the age and concomitant comorbidities of COVID-19 patients largely determine the clinical course of COVID-19, D-dimer, CRP, ferritin, cardiac troponin I and IL-6 may act as predictors for severe COVID-19." (PMID 34262116, 2021). "In COVID-19 patients, Mucoromycota was positively correlated with Fusicatenibacter, Aspergillus niger was positively correlated with diarrhoea, and Penicillium citrinum was negatively correlated with C-reactive protein (CRP)." (PMID 33850296, 2021). "To find an alternative disease timer, we compared the testing frequency of routine laboratory parameters such as the acute phase inflammatory marker CRP, the inflammatory cytokine interleukin 6 (IL-6), myoglobin and cardiac troponin that have previously been correlated to COVID-19 severity." (PMID 34307391, 2021). "CRP and IL-6 are inflammation-related biomarkers that have moderate-to-high correlation with the NLR, and these biomarkers are also associated with the unfavorable aspects of COVID-19 and duration of hospitalization." (PMID 33726485, 2021). "Moreover, laboratory parameters assayed in COVID-19 patients (CRP, ferritin, LDH, D-dimer, lymphocytes and neutrophils count, RDW-SD, PCT) showed a trend of association with the sFlt-1 interquartile values." (PMID 34620968, 2021). "Further, it is interesting that the association between plasma ACE2 and maximal acuity within 28 days in COVID-19 patients was statistically significant also after correction for age, BMI, pre-existing medical conditions, and the laboratory tests CRP, absolute neutrophil count and D-dimer." (PMID 34086837, 2021). "However, CRP has also been shown to be above the normal range in most COVID-19 patients, and increases in troponins, CK-MB, and BNP." (PMID 34206074, 2021). "These diseases were also closely related to CRP levels in COVID-19." (PMID 34447386, 2021). "Furthermore, DM is associated with increased C-reactive protein (CRP), fibrinogen, and D-dimer that can lead to the hypercoagulation state observed in COVID-19 patients with DM." (PMID 34205044, 2021). "The hematological profile of a patient typically affected with coronavirus disease 2019 (COVID-19) showed lymphopenia with an altered neutrophil-lymphocyte ratio, raised inflammatory markers like D-dimer, interleukin 6 (IL-6), C-reactive protein (CRP), lactate dehydrogenase, and serum ferritin." (PMID 34966605, 2021). "More importantly, S100A12 expression at hospital admission was robustly correlated with future quantitative indexes of disease severity and outcome in COVID-19 patients, superior to established prognostic markers including CRP, PCT, d-dimer, ferritin, LDH and fibrinogen." (PMID 34108608, 2021). "The CRP (OR: 1.103; 95% CI: 1.060–1.148; p < 0.001) and total bilirubin (OR: 1.612; 95% CI: 1.330–1.954; p < 0.001) levels were independent predictors of myocarditis in COVID-19." (PMID 34928467, 2021). "A risk factor for higher mortality of patients diagnosed with DM and COVID-19 was, among others, elevated C-reactive protein (aOR 1.12 [95% CI 1.00, 1.24]; P = 0.043), implicating C-reactive protein may identify high risk patients during hospitalization." (PMID 34416856, 2021).